HDAC3 (histone deacetylase 3)
Diseases named in the same sentence as HDAC3 in open-access papers (continued):
Sharing a sentence is not in itself a finding about the gene and the disease.
female infertility (2 papers, 2025 to 2026). Diminished or absent ability of a female to achieve conception. "In this study, we found that aberrantly high expressed HDAC3 in ovulatory GCs after LH induction is an important pathogenic factor for female infertility." (PMID 39938798, 2025). "In this study, using a mouse model with GC-specific overexpression of Hdac3 (Hdac3OE), we demonstrated that abnormal HDAC3 expression in ovulatory GCs after the LH surge was a causative factor leading to female infertility." (PMID 39938798, 2025). "Our previous study demonstrated that loss of histone deacetylase 3 (HDAC3) impairs endometrial receptivity and decidualization, resulting in female infertility." (PMID 41984129, 2026). "The results showed that abnormally high levels of HDAC3 in ovulatory GCs inhibited LH induction on oocyte maturation and ovulation, resulting in female infertility." (PMID 39938798, 2025). "Therefore, this study was designed to explain whether abnormally elevated HDAC3 in GCs is the pathological factor resulting in female infertility." (PMID 39938798, 2025).
fibrosarcoma (2 papers, 2013 to 2015). A malignant mesenchymal fibroblastic neoplasm affecting the soft tissue and bone. "Conditional deletion of Hdacs1,2 in fibrosarcoma cells led to a significant increase in H4K5ac, whereas deletion of Hdac3 led to a subtle increase in H4K5ac." (PMID 23947532, 2013).
gout (2 papers, 2024 to 2025). A condition characterized by painful swelling of the joints, which is caused by deposition of urate crystals. "Simultaneously, animal model validation showed that HDAC3-deficient mice exhibited significantly reduced inflammation in gout models, providing evidence for the development of selective HDAC3 inhibitors." (PMID 41311848, 2025). "We firstly investigated the influence of HDAC3 deficiency on MSU crystals-induced inflammation in gout mouse models in vivo." (PMID 38711064, 2024). "It was observed that HDAC3 KO mice had a favorable phenotype to reduce acute gouty arthritis since macrophage-specific HDAC3 deficiency in MSU crystals-induced footpad edema and ankle swelling models." (PMID 38711064, 2024). "Our research focused on macrophage-specific HDAC3 deficiency in development and function of MSU-induced inflammation via MSU-induced gout mouse models." (PMID 38711064, 2024). "Further studies on the application of HDAC3 inhibitor in vivo were expected to evidence that targeting HDAC3 could be one of promising treatment for gout." (PMID 38711064, 2024). "Deficiency of HDAC3 in macrophage alleviates MSU crystals-induced gouty inflammation through inhibition of TLR2/4 driven IL-6/STAT3 signaling pathway, suggesting that HDAC3 could contribute to a potential therapeutic target of gout." (PMID 38711064, 2024). "Studies have shown that the absence of HDAC3 in macrophages alleviates MSU crystal-induced gout inflammation by inhibiting the TLR2/4-driven IL-6/STAT3 signaling pathway, suggesting that HDAC3 may serve as a potential therapeutic target for gout." (PMID 41311848, 2025).
hyperandrogenism (2 papers, 2020 to 2023). Excessive secretion of androgens from the adrenal glands or gonads. "Hyperandrogenism increases the expression of HDAC3 in granulosa cells, which causes ovarian dysfunction in women with PCOS." (PMID 32992734, 2020). "Hyperandrogenism promotes epigenetic modifications of histone deacetylase 3 (HDAC3), peroxisome proliferator-activated receptor gamma 1 (PPARG1), and nuclear corepressor 1 (NCOR1) genes in granulosa cells of PCOS women." (PMID 37854189, 2023). "Another study conducted on animal models, and in women with PCOS, showed a significant influence of hyperandrogenism on epigenetic modifications leading to increased expressions of HDAC3 genes in granulosa cells in PCOS-afflicted women." (PMID 32992734, 2020). "Women with PCOS and hyperandrogenism showed higher HDAC3 expression than women with PCOS without hyperandrogenism." (PMID 32992734, 2020). "This study showed statistically significant differences in the level of HDAC3 expression between the study group (women with PCOS and hyperandrogenism) and the control group (women with PCOS without hyperandrogenism)." (PMID 32992734, 2020).
Hypertension (2 papers, 2015 to 2019). The presence of chronic increased pressure in the systemic arterial system. "In our current study, we found that MS-275, a class I HDAC-selective inhibitor (HDAC1, HDAC2, and HDAC3), lowered blood pressure, reduced blood vessel thickness, and inhibited inflammation in an Ang II-induced hypertensive animal model." (PMID 30830950, 2019). "HDAC3 inhibition increases MR acetylation, which reduces its transcriptional activity and prevents the development of hypertension in deoxycorticosterone acetate-induced hypertensive rats." (PMID 26305553, 2015). "Recently, it was reported that HDAC3 and HDAC4 mediate hypertension such as in deoxycorticosterone acetate (DOCA)-salt-induced hypertensive rat and SHR, respectively." (PMID 30830950, 2019).
Intellectual disability (2 papers, 2023 to 2024). "In humans, mutations in HDAC3 lead to intellectual disability." (PMID 36983897, 2023).
interstitial lung disease (2 papers, 2020 to 2022). A diverse group of lung diseases that affect the lung parenchyma. "We investigated the roles of histone deacetylase 3 (HDAC3) involved in RA-associated interstitial lung disease (ILD) fibrosis." (PMID 33343379, 2020).
kidney cancer (2 papers, 2020 to 2021). Primary or metastatic malignant neoplasm involving the kidney. "A previous study reported that GLIS2 interacts with HDAC3 and regulates gene expression in several kidney cancer cells." (PMID 32483180, 2020).
mastitis (2 papers, 2023 to 2025). Inflammation of breast tissue during lactation or postpartum due to an obstructed duct or infection. "Mice fed a fiber-enriched diet (e.g., inulin) presented increased relative abundances of SCFA-producing bacteria and elevated fecal SCFA levels, which alleviated S. aureus-induced mastitis by activating HDAC3-mediated antimicrobial programs in macrophages." (PMID 41139776, 2025). "Specifically, antibiotic-induced gut dysbiosis depletes commensal bacteria such as Clostridium and Lactobacillus reuteri and impairs the production of SCFAs and indole derivatives, which limit pathogen-induced mastitis by inhibiting HDAC3 and activating AhR, respectively." (PMID 41139776, 2025).
metastatic melanoma (2 papers, 2021). A melanoma that has spread from its primary site to another anatomic site. "HDAC-3, -5, -6 and -8 have been associated with primary and metastatic melanoma cases." (PMID 34441281, 2021).
myocardial ischemia (2 papers, 2024 to 2025). A disorder of cardiac function caused by insufficient blood flow to the muscle tissue of the heart. "Kaempferol alleviates myocardial ischemia injury by reducing oxidative stress via the HDAC3-mediated Nrf2 signaling pathway." (PMID 40533778, 2025).
neuropathies (2 papers, 2018 to 2024). "Here, we show a distinct role for HDAC3, in that, while dispensable for the formation of mSCs, it is essential for the stability of the myelin sheath once formed—with loss resulting in progressive severe neuropathy in adulthood." (PMID 30517863, 2018). "show that a switch between HDAC1/2 and HDAC3 is responsible for the entry of myelinating Schwann cells into homeostasis with HDAC3−/− Schwann cells myelinating normally but “overshooting,” resulting in severe neuropathies in adult mice." (PMID 30517863, 2018).
Osteopenia (2 papers, 2010 to 2021). Osteopenia is a term to define bone density that is not normal but also not as low as osteoporosis. "When taken into account the fact that agomir‐4286 distinctly downregulated the level of HDAC3 in mice, we concluded that alcohol inhibited the angiogenesis in alcohol‐induced osteopenia via upregulating HDAC3." (PMID 33973278, 2021). "In vivo, alcohol feeding dramatically increased the level of HDAC3 in the osteopenia model of mice, and agomir‐4286 distinctly downregulated HDAC3 in mice treated with alcohol." (PMID 33973278, 2021). "The current study, for the first time, demonstrated that miR‐4286 can against alcohol‐induced osteopenia by the dual regulation of osteogenesis as well as angiogenesis in mice, via modulating the expression of HDAC3." (PMID 33973278, 2021). "Our experimental results showed that miR‐4286 protected alcohol‐induced osteopenia via targeting HDAC3 based on the following solid evidence." (PMID 33973278, 2021). "Our results indicate that sustained Hdac3 suppression is likely to produce osteopenia and potentially fractures." (PMID 20628553, 2010). "miR‐4286 might function via intimate osteogenesis‐angiogenesis pathway to alleviate alcohol‐induced osteopenia via targeting HDAC3." (PMID 33973278, 2021). "Taken together, for the first time, we demonstrated that miR‐4286 might function via intimate osteogenesis‐angiogenesis pathway to alleviate alcohol‐induced osteopenia through the regulation of HDAC3." (PMID 33973278, 2021). "We firstly demonstrated that miR‐4286 might function via intimate osteogenesis‐angiogenesis pathway to alleviate alcohol‐induced osteopenia via targeting HDAC3." (PMID 33973278, 2021). "Taken together, these results demonstrated that miR‐4286 might prevent alcohol‐induced osteopenia via targeting HDAC3 by dual regulation of osteogenesis and vascularization." (PMID 33973278, 2021).
peripheral T cell lymphoma (2 papers, 2022 to 2025). "Chidamid, an oral HDAC inhibitor of the benzamide class with specificity for HDAC1, HDAC2, HDAC3, and HDAC10 subtypes, has been approved for the treatment of relapsed or refractory peripheral T cell lymphoma." (PMID 41049003, 2025). "Tucidinostat, a selective HDAC inhibitor having specificity for HDAC1, HDAC2, HDAC3, and HDAC10 subtypes, has been approved for the treatment of relapsed or refractory peripheral T cell lymphoma and is under clinical development globally for various other neoplastic and non-neoplastic diseases." (PMID 36352411, 2022).
pneumonia (2 papers, 2021 to 2026). An acute, acute and chronic, or chronic inflammation focally or diffusely affecting the lung parenchyma, caused by an infection in one or both of the lungs (by bacteria, viruses, fungi, or mycoplasma.). "Cardiolipin-induced SUMOylation inhibits IL-10 production by lung CD11b þLy6GintLy6CloF4/80 þ cells because of the recruitment of a repressive nuclear receptor corepressor (NCOR)/ histone deacetylase 3 (HDAC3) complex to the IL-10 promoter, ending in persistent inflammation during pneumonia." (PMID 33467433, 2021). "Mechanistically, valeric acid enhanced ciliary biogenesis and function by inhibiting HDAC3, activating Wnt signaling, and upregulating FOXJ1, which ultimately improved clinical outcomes in severe pneumonia." (PMID 41601983, 2026).
renal carcinoma (2 papers, 2021 to 2023). A carcinoma arising from the epithelium of the renal parenchyma or the renal pelvis. "HDAC-3 overexpression has been inversely associated with pT status in a cohort of renal carcinomas (RCC), especially of the papillary histologic type." (PMID 33799478, 2021). "Histone deacetylases class 1 (HDAC1, HDAC2, HDAC3, and HDAC8) are expressed ubiquitously in almost all types of cancer except renal cancer." (PMID 37345150, 2023).
renal cell carcinoma (2 papers, 2008 to 2022). "In renal cell carcinomas moderate to strong nuclear HDAC1, HDAC2 and HDAC3 immunoreactivity was detected in 55.7%, 56.6% and 13.2% of cases, respectively." (PMID 19099586, 2008).
schizophrenia (2 papers, 2018 to 2022). A major psychotic disorder characterized by abnormalities in the perception or expression of reality. "A recent study has linked HDAC3 expression to schizophrenia." (PMID 35669261, 2022). "Together, the results indicate that co-regulation of H3K9ac by HDAC1 and HDAC3 is important to both embryonic brain development and neuro-differentiation as well as the pathophysiology of a schizophrenia-like phenotype." (PMID 28300292, 2018). "Conversely, the hippocampi of schizophrenia-like animals showed H3K9 deacetylation that was regulated by an increase in both HDAC1 and HDAC3." (PMID 28300292, 2018). "We observed that the hippocampi of schizophrenia-like rats had very low levels of H3K9 acetylation but displayed increases in both HDAC1 and HDAC3 levels (d1–d3)." (PMID 28300292, 2018).
short bowel syndrome (2 papers, 2023 to 2025). "In the intestine of rats with short bowel syndrome, phytate increased IP3 levels, which stimulated HDAC3 activity, but did not alter HDAC3 gene expression levels." (PMID 39942756, 2025).
spinal cord injuries (2 papers, 2016 to 2021). "Recently, increased HDAC3 and TNFα and decreased miRNA-130a expression has been observed in PBMCs from patients with spinal cord injuries." (PMID 27904654, 2016). "Valproic acid treatment inhibited HDAC3 expression and activity, enhanced STAT1, and acetylated NF-κB p65 after spinal cord injury (SCI)." (PMID 34764819, 2021).
thymic epithelial tumors (2 papers, 2023 to 2025). "In a clinical study on thymic epithelial tumors (TET), PD-L1 expression was positively correlated with cytoplasmic expression of HDAC3 in TET tumor cells." (PMID 40006729, 2025). "In this study we attempt the first comprehensive evaluation of six class I (HDAC1, HDAC2, HDAC3) and II HDACs (HDAC4, HDAC5, HDAC6) expression patterns in thymic epithelial tumors (TETs), with the aim of identifying their possible association with a number of clinicopathological parameters." (PMID 36901692, 2023).
acute liver failure (1 paper, 2023). Rapid deterioration of liver function causing encephalopathy and coagulopathy. "Thus, inhibition of GSK3β activity could improve cell death levels in acute liver failure by modulating the activity levels of the TRAF6/HDAC3/TAK1 molecular pathway." (PMID 37443080, 2023).
aortic valve disease (1 paper, 2025). "Although our previous studies have established roles for HDAC3 in cardiac development and lymphatic vascular function, its specific contribution to aortic valve disease has not been investigated." (PMID 40923319, 2025).
aortic valve stenosis (1 paper, 2025). Aortic valve stenosis (AVS) is a condition characterized by narrowing of the heart's aortic valve opening. "To investigate the molecular mechanisms underlying aortic valve stenosis following Hdac3 deletion, we performed bulk RNA-sequencing on aortic valves from control and Hdac3-knockout mice." (PMID 40923319, 2025). "Given that HDAC3 plays a unique role among class I HDACs in regulating H3K27ac, a histone mark critical for enhancer activity and gene transcription, it is important to develop a mouse model to mechanistically investigate its function in aortic valve stenosis and associated epigenetic remodeling." (PMID 40923319, 2025). "Hdac3 prevents aortic valve stenosis by maintaining epigenetic and structural homeostasis in valve fibroblasts." (PMID 40923319, 2025). "Functional assessment via echocardiography demonstrated increased peak velocity across the aortic valve by 40 weeks of age in Hdac3-knockout mice, consistent with the development of aortic valve stenosis, while left ventricular ejection fraction remained comparable to controls." (PMID 40923319, 2025). "By uncovering HDAC3 as a regulatory node in this pathway, our work opens avenues for targeted therapeutic strategies to modulate mitochondrial biogenesis and redox homeostasis to prevent or slow the progression of aortic valve stenosis." (PMID 40923319, 2025). "Although HDAC3 is a key deacetylase that targets H3K27ac, its role in regulating gene expression and tissue remodeling in aortic valve stenosis has not been investigated." (PMID 40923319, 2025). "Mice lacking HDAC3 in aortic valves developed aortic valve stenosis, disrupted collagen organization, increased H3K27ac, and premature mortality." (PMID 40923319, 2025).
Atrophy (1 paper, 2020). Any weakening or degeneration, especially through lack of use. "The conditional knockout of HDAC3 in RGCs resulted in obvious amelioration of optic nerve crush-induced nuclear atrophy, including Histone4 deacetylation, heterochromatin formation, and the loss of nuclear structure; RGC apoptosis was also apparently reduced." (PMID 32190700, 2020).
autoimmune hepatitis (1 paper, 2024). Hepatitis caused by autoantibodies. "Nimbolide inhibits HDAC3 expression in autoimmune hepatitis (AIH) mice’s liver and AML12 cells to inhibit inflammation." (PMID 38571915, 2024).
bladder cancer (1 paper, 2022). "A further two (EGFR and HDAC3) are known to be highly expressed in bladder cancer and are also being targeted by drugs for bladder cancer." (PMID 35035776, 2022). "Interestingly, several of our potential targets are currently in clinical trials for the treatment of bladder cancer including EGFR, HDAC3, FGFR3, ERBB3." (PMID 35035776, 2022).
brain infarction (1 paper, 2022). Tissue necrosis in any area of the brain, including the cerebral hemispheres, the cerebellum, and the brain stem. "In addition, the suppression of HDAC3 also suppresses oxidative stress which in turn decreases brain infarction area, brain edema, and neurological deficit." (PMID 39281061, 2022).
breast invasive ductal carcinoma (1 paper, 2020). "Immunohistochemical staining of HDAC1, HDAC2, and HDAC3 in 161 samples from breast invasive ductal carcinoma patients, including 63 patients with brain metastasis, was performed using the standard streptavidin‐peroxidase method." (PMID 32686908, 2020).
cardiomyopathy (1 paper, 2013). A disease of the heart muscle or myocardium proper. "HDAC3 knockout mice are embryonic lethal due to cardiomyopathy." (PMID 24160175, 2013).
cerebellar degeneration (1 paper, 2013). Degeneration of the cerebellum. "Future studies would directly analyze this role by looking at the affect of altered HDAC3 levels in a SCA7 transgenic model, particularly on behavioural phenotypes, cerebellar degeneration and morbidity." (PMID 24160175, 2013).
cervical tumor (1 paper, 2018). "We analyzed the expression of PIWIL2 and HDAC3 by tissue microarray containing 30 pairs of cervical tumor tissues and adjacent normal tissues, and found that both PIWIL2 and HDAC3 were more highly expressed in tumor tissues than those in adjacent tissues." (PMID 29555935, 2018).
chondrosarcoma (1 paper, 2020). A malignant cartilaginous matrix-producing mesenchymal neoplasm arising from the bone and soft tissue. "HDAC1 and HDAC3 are most abundantly expressed in healthy human cartilage, and we showed that these subtypes are also highly expressed in chondrosarcoma cell lines." (PMID 33266275, 2020).
chromophobe carcinoma (1 paper, 2021). "For example, in RCC (including chromophobe carcinoma, ccRCC, and papillary cell carcinoma), low expression of HDAC1, HDAC2, HDAC3, HDAC8, HDAC10 and high expression of HDAC5, HDAC7, HDAC11 have longer survival time." (PMID 34308568, 2021).
cleft palate (1 paper, 2022). Cleft palate is a fissure type embryopathy that affects the soft and hard palate to varying degrees. "The deletion of Hdac3 and Hdac8 in CNCCs results in various craniofacial deformities, including cleft palate, microcephaly, and calvarial bone defects." (PMID 35242053, 2022). "The conditional deletion of Hdac3 in CNCCs in the mouse results in cleft palate, microcephaly, frontal bone defects, and improper formation of the zygomatic arch due to enhanced expression of Msx1/2 and increased apoptosis of CNCCs." (PMID 35242053, 2022).
colorectal tumors (1 paper, 2022). "In consistent with our findings, high expression of HDAC3 has also been identified in colorectal tumors in association with tumor differentiation grade." (PMID 36266728, 2022).